BAP1 (BRCA1 associated deubiquitinase 1)
Diseases named in the same sentence as BAP1 in open-access papers (continued):
Sharing a sentence is not in itself a finding about the gene and the disease.
tumor (continued). "This tumor suppressor gene encodes a ubiquitin carboxyl-terminal hydrolase that regulates with downstream targets involved in cell breakdown and replication, with BAP1 inactivation resulting in uncontrolled cell proliferation." (PMID 35565216, 2022). "Mutational inactivation of BAP1 in UM may lead to a suppressive TIME at least in part by upregulation of PROS1 in tumor cells and phospho-activation of MERTK in tumor-associated macrophages." (PMID 35954340, 2022). "Thus far, radiomic signatures have been linked to molecular factors with established prognostic associations; for instance, BAP1 mutation with aggressive tumor phenotype or ccB with worsened cancer specific survival." (PMID 35159060, 2022). "Due to BAP1 immunomodulatory functions, as well as lymphocyte infiltration and inflammatory tumor environment seen in some BAP1-deficient tumors, BAP1 alterations are seen as possible biomarkers that may help predict response to immunotherapy." (PMID 35381901, 2022). "This tumor showed loss of expression of BAP1 with the preserved expression of mTAP." (PMID 35565429, 2022). "Tumours with defects in homologous recombination repair may be susceptible to PARP inhibitors including tumours with BAP1-deficiency." (PMID 36138075, 2022). "The mean number of tumor cells with loss of BAP1 expression was 251 520 892 (SD 368 488 894)." (PMID 33903674, 2021). "In univariate Cox regression analysis, high nuclear grading (HR = 1.95, p = 0.001), unfavorable tumor architecture (HR = 2.69, p = 0.001), high average mitotic count (HR = 1.12, p = 0.003), and BAP1 tumor positivity (HR = 1.80, p = 0.030) were associated with shorter survival." (PMID 33955203, 2021). "We also revealed that the number and type of metastases is irrelevant to the prognostic mutation status of the tumor, showing that both BAP1- and SF3B1-mutated UM can result in solitary and miliary metastases, indicating that other processes lay ground to the different metastatic patterns." (PMID 34771480, 2021). "Two of 93 patients (2.2%) showed BAP1 loss by IHC in clear cell RCC tumor cells." (PMID 34767027, 2021). "Thus, we aim to make estimations of the origin and dynamic evolution of the BAP1 mutated tumor cell clone in UM." (PMID 33903674, 2021). "Similarly, tumor cells with loss of BAP1 expression had significantly larger mean volume (2657 μm3, SD 1283) than those with retained expression (1593 μm3, SD 602, p = 0.027)." (PMID 33903674, 2021). "The tumours with M3/loss of BAP1 often show an inflammatory phenotype." (PMID 34439175, 2021). "Notably, even in tumours arising from germline BAP1 mutation, non-tumour cells express a single wild-type copy and hence produce a positive IHC response." (PMID 34209209, 2021). "To investigate the potential mechanism underlying BAP1 in the regulation of tumor suppression, we analyzed the gene expression profile of BAP1‐knockdown U2OS cells, which was obtained from the Gene Expression Omnibus (GEO) public microarray dataset (accession ID: GSE23035)." (PMID 33155366, 2021). "In both patients, canonical mutations in GNA11 and BAP1 were present in all tumor samples." (PMID 34400647, 2021).
tumor (continued). "Metastasis-free survival after BAP1 mutation was defined as the proportion of patients not having suffered symptomatic and/or radiologically detectable metastases at a specific time after the estimated appearance of the first tumor cell with loss of BAP1 expression." (PMID 33903674, 2021). "Similarly, tumor cells with loss of BAP1 protein expression had significantly larger volume (2657 vs. 1593 μm3, p = 0.027)." (PMID 33903674, 2021). "Thus, we provide a mathematical explanation of the occurrence of micrometastases during the tumor’s infancy and underscore the importance of BAP1 mutation in tumorigenesis." (PMID 33903674, 2021). "Inactivating mutations in BAP1, a tumour suppressor gene located on chromosome 3p, are found in approximately 47% of primary UM and 84% of metastatic UM cases, consistent with the association between BAP1 mutations and poor prognosis." (PMID 35056909, 2021). "Future studies will need to further address the molecular mechanisms underlying the tumor suppressor activities of BAP1 in different cell types, in the light of its apparent positive role in the regulation of cell proliferations in non-transformed cells of many tissues." (PMID 33912157, 2021). "Tumor burden might be somewhat higher in BAP1-mutated tumors, as suggested by ctDNA and LDH levels, although differences in these metrics were not significant." (PMID 34453044, 2021). "We suggest that a group of miRs suppress HLA expression and that during tumour progression (associated with addition of copies of chromosome 8q and loss of one chromosome 3 and loss of BAP1 expression) the HLA-suppressive miRNAs are lost and the stimulatory ones get expressed." (PMID 34439175, 2021). "Consistent with the previous studies, we demonstrated that BAP1 inactivation was associated with immune infiltration and immune marker gene set expression, indicating the BAP1 may regulate tumor immunology." (PMID 31954372, 2020). "Furthermore, several studies showed that BAP1 loss or modification is associated with different tumor phenotypes and clinical outcomes." (PMID 33585209, 2020). "The endpoint of asbestos-induced damage is the generation of an inflammatory microenvironment that may support tumor growth in individuals with predisposition, for instance due to loss of BAP1." (PMID 32392897, 2020). "In addition to missense mutations disrupting catalytic activity, nonsense mutations that truncate the BAP1 protein are also recurrent in sequenced patient tumours." (PMID 33105797, 2020). "Moreover, germline mutated BAP1 carriers have a larger tumor diameter and more frequently reported ciliary body involvement." (PMID 33396957, 2020). "Our analysis suggested that BAP1 mutations and chromosome alterations may determine the tumor immune state and immune infiltration of UM." (PMID 31954372, 2020). "Interestingly, BRCA1-associated protein-1 (BAP1) is a tumor-suppressor gene placed on chromosome 3, and it is mutated in 47% of primary UM and up to 91% of metastatic UM." (PMID 32992823, 2020). "Additionally, the methylation groupings were more accurate in predicting the development of metastasis in this cohort than other significant markers of UM progression, including chromosome 3 loss, BAP1 mutations, and tumor features used to predict prognosis." (PMID 33092094, 2020). "The studies in these models proved that the BAP1 gene was a bona fide tumor suppressor whose heterozygous germline mutation increases the risk of MPM development in BAP1 mutation carriers when exposed to environmental carcinogens, in particular asbestos fibers." (PMID 32882916, 2020). "Additionally, tumor characteristics of the BAP1-TPDS-associated CM are quite unique, exhibiting distinct morphology and histology which are similar to Atypical Spitz Tumors, which are substantially different from other common CM sub-types." (PMID 32028647, 2020).
tumor (continued). "The most of BAP1 mutations lead to the absence of the functional protein, as well as the loss of chromosome 3 may result in BAP1 monosomy, thus causing reduced levels of the BAP1 protein, suggesting a tumor suppressive role for this gene in UM." (PMID 33371395, 2020). "Of potential relevance was also the downregulation of TIM-3 and TIGIT ligand-related genes after restoring BAP1 function, indicating potential upregulation on BAP1 loss that may have consequences for tumor–immune interactions." (PMID 32313009, 2020). "Furthermore BAP1 has been found to be mutated in tissue from sporadic malignant renal tumors, which are associated with a high tumor grade and bad prognosis." (PMID 31034483, 2019). "The investigators went on to show that BAP1 loss in PeM is associated with a more inflamed tumor microenvironment and propose that this finding could be useful as a predictive marker of responsiveness to immune checkpoint inhibitors (ICIs)." (PMID 30914057, 2019). "BAP1 encodes a deubiquitylase that forms protein complexes that are implicated in several pathways along with cell cycle, cell differentiation, and DNA damage response and it has been described to act as a tumor suppressor in various cancers." (PMID 31330784, 2019). "We wondered whether the expression of these genes may be related to genetic progression (early 8q gain and later BAP1 loss) in the 54 cases with data on tumour genetics and mRNA gene expression." (PMID 31337000, 2019). "Furthermore, other candidate susceptibility genes for tumor types associated with BAP1-TPDS are discussed, which can be included in gene panels when testing patients." (PMID 31382694, 2019). "Tumours in sHLA-positive eyes were significantly larger, more frequently involved the ciliary body, and more often showed monosomy 3, gain of chromosome 8q and loss of BAP1 staining." (PMID 31426578, 2019). "In order to determine whether the association between loss of BAP1 and changes in the NFkB pathway occurs in the tumor cells themselves, we excluded the 33% of tumors with the highest CD8 score, leaving a total of 43 tumors." (PMID 31382450, 2019). "In addition, inactivating germline mutations result in the BAP1 tumor predisposition syndrome, associated with a high risk of tumor development." (PMID 31903168, 2019). "Manual assessment of the level of expression of the tumor suppressor BRCA1-associated protein 1 (BAP1) in tumor cell nuclei can identify patients with a high risk of developing metastases, but may suffer from poor reproducibility." (PMID 31623293, 2019). "Whether BAP1 loss might be more broadly applicable across different cancer types as a biomarker for an immune-inflamed tumor microenvironment will require further studies." (PMID 30914057, 2019). "However, the frequency of BAP1 mutation and down-regulation varies among tumor types, and little is known about the function of BAP1 silencing in cancer cells." (PMID 30395583, 2018). "The findings are in accordance with previous reports that reduced expression or inactivation of BAP1 in tumors, which often results from germline-inactivating or somatic-inactivating BAP1 mutations or deletions, increases tumor susceptibility, or predicts worse clinical outcomes." (PMID 30305612, 2018). "Breast cancer type 1 susceptibility protein-associated protein-1 (BAP1) has been reported to be a broad-spectrum tumor suppressor in many tumor types, yet its role in ICC remains unknown." (PMID 30305612, 2018). "Similarly, LOH3 was always present in 100% of tumor cells, whereas the associated BAP1 mutations were occasionally found in a subclone." (PMID 29317634, 2018). "This need for a tumor-initiating Gq mutation could explain why only a minority of individuals with germline BAP1 mutations develop UM45." (PMID 29317634, 2018). "Our data support the use of loss of function of BAP1 as a genomic stratification tool to identify rTRAIL-sensitive MM tumours, an approach that may extend to other cancer subtypes." (PMID 29345617, 2018).
tumor (continued). "However, as BAP1 mutations are known to occur in the germline in some cases, we analyzed all blood samples independently of their matched tumor using MuTect2, with which we identified two cases with germline BAP1 mutations (MM87 and A8KN)." (PMID 29317634, 2018). "Thus, the pathways regulated by BAP1 that link its loss to metastasis – as it is in UM tumors – also depend on the tissue and lineage contexts of the tumor." (PMID 30400891, 2018). "While next-generation sequencing reveals MM BAP1 mutation rates in the order of 20–30%, immunohistochemical analysis has identified loss of BAP1 function in up to 67% of MM tumours opening our biomarker-driven approach to a significant proportion of MM patients." (PMID 29345617, 2018). "Alternatively, in some cases it is possible the during tumor evolution, BAP1 mutation on one copy of chromosome 3 could precede the loss of the other copy of chromosome 3." (PMID 30477459, 2018). "It has been proposed that the loss of BAP1 function may favor the generation of an inflammatory tumor environment." (PMID 28229253, 2017). "BAP1 loss has been reported to define a new class of ccRCC and acts as a tumor suppressor." (PMID 29158875, 2017). "Interestingly, BAP1 mutations in 15% of all ccRCC have been reported together with SETD2 mutations being more frequent in higher stage tumours and associated with worse prognosis." (PMID 28486536, 2017). "The germline mutation of BAP1 has been associated with high risk of neoplasms." (PMID 29158875, 2017). "BAP1 expression is associated with multiple tumor types and high tumor phenotype penetrance." (PMID 29018224, 2017). "Shared mutations in patients 1 and 2 could potentially be targeted to eradicate the underlying field disease – patient 1 presents with a shared BAP1 mutation between the four tumours and BAP1 is mutated in all samples from the urothelium." (PMID 28916750, 2017). "Notably, similar histological appearances have been recorded for tumours with either somatic or germline BAP1 mutations." (PMID 28062663, 2017). "Our results showed that the four tumor samples harbored a wild-type BAP1 allele, but all samples either expressed a cytoplasmic delocalized BAP1 or did not express the protein, suggesting a convergent inactivation mechanism of BAP1 in GNAQ-mutated samples." (PMID 27057633, 2016). "The BRCA-1 associated protein-1 (BAP1) tumor suppressor gene, located on chromosome 3p21, codes the ubiquitin carboxy-terminal hydrolase enzyme which is among the enzymes responsible for tumor-suppressing activity in cancer cells, and regulates the activity of some proteins through deubiquitination." (PMID 27800275, 2016). "BAP1 is a critical tumor suppressor that is frequently mutated in human cancer." (PMID 26739236, 2016). "Concerning the prognostic significance of BAP1, PBRM1 and SETD2 mutational status, BAP1 loss correlates with high Fuhrman nuclear grade and mTORC1 activation, higher tumor stage, and worst overall survival, while PBRM1 mutations seem to identify a favorable group of ccRCC." (PMID 26452128, 2015). "Three cell cultures, all of which were derived from BAP1 mutant primary tumors, exhibited anchorage independent growth and also formed tumors in mice, suggesting that BAP1 loss may enhance tumor growth in vivo." (PMID 25952750, 2015). "Combined with the fact that these same cell cultures were also tumorigenic suggests that BAP1 loss may also enhance tumor growth in vivo." (PMID 25952750, 2015). "Assessment of the BAP1 locus revealed wild-type alleles in both the tumor and germline." (PMID 25798586, 2015). "Finally, correlating BAP1 mutation and cancer outcome at molecular level will help us to understand tumor biology and potential therapeutic development to combat cancer in general." (PMID 26680512, 2015).
tumor (continued). "Three out of five cells, all of which were derived from BAP1 mutant primary tumors, exhibited anchorage independent growth and also formed tumors in vivo, suggesting that BAP1 loss may enhance tumor growth in vivo." (PMID 25952750, 2015). "This tumor also contained two distinct mutations in BAP1, each detected in different cores." (PMID 25124064, 2014). "The suggested progression-promoting effect of mutated BAP1 is in line with the tumor suppressive function of intact BAP1 as a deubiquitylase required for efficient assembly of the homologous recombination (HR) factors BRCA1 and RAD51 after DNA double-strand breaks (DSBs)." (PMID 25593912, 2014). "If this were the case and the critical event triggered by BAP1 loss was the escape of tumor cells from the eye, then our available xenograft models may be insufficient to model this." (PMID 23915344, 2013). "BRCA1–associated protein 1 (BAP1) is a tumor suppressor gene located on chromosome 3p21." (PMID 22935333, 2012). "Our observations revealed a notable downregulation of BAP1 expression in a subset of tumor tissues, which was associated with a significantly poorer prognosis for those patients, indicating BAP1 deficiency might also plays a significant role in the progression and metastasis of PDAC." (PMID 40083694, 2025). "However, these tumor-suppressive effects of BAP1 are abolished by inactivating mutations." (PMID 40607251, 2025). "Among their two primary therapeutic mechanisms, the potential of OVs to inhibit the protein synthesis in tumor cells and destroy infected tumor cells by self-replication is the most probable mechanism underlying the superior efficacy of JX-594 in the reduction of BAP1-mutant tumors." (PMID 40856833, 2025). "A preclinical study discovered that, when BAP1 is mutated, the levels of HIF-1α are significantly reduced and suggested that the improved prognosis observed in PM with BAP1 mutations may be linked to the reduced HIF-1α levels in the tumor cell and in the microenvironment." (PMID 40361508, 2025). "BAP1 mutations may induce an increase in the number or activity of tumor-infiltrating immune cells." (PMID 40856833, 2025). "BAP1 loss may also help tumor cells evade immune detection, thereby promoting metastasis." (PMID 39061150, 2024). "Moreover, in this study, VHL represented the predominant group of mutations (50.5%) but significant results were founded only for BAP1 mutation and its association with ill-defined tumor margins and the presence of calcification and for MUC4 mutation and its connection with exophitic growth." (PMID 38666933, 2024). "Thus, it would be of particular interest to examine whether knockdown or inhibition of MFAP4, NPTX1, and/or HMGA2 suppresses tumor development of BAP1-deficient MMe cells." (PMID 37479714, 2023). "Within the mesothelial context, we find that BAP1 loss leads to the dysregulation of a range of genes involved in stem cell specification, with a module of these genes consistently upregulated within both the generated isogenic cell‐line model and tumour tissue." (PMID 36740402, 2023). "Therefore, these evidences allowed us to hypothesize in the current study that BAP1 mutations might regulate the tumor immune microenvironment to affect the growth and metastasis of UM, with the involvement of the NF-κB signaling pathway." (PMID 37710185, 2023). "Indeed, BAP1 deletions and loss of function mutations are common in many cancers, and in these tumors, xc− activity would be likely to provide extracellular cystine and tumor protection." (PMID 37486582, 2023). "It is necessary to examine whether genome instability causes tumorigenesis in cancers that arise by BAP1 loss/inactivation and to what extent the role of BAP1 in genome stability contributes to tumor suppression relative to that of other mechanisms, such as apoptosis." (PMID 37009801, 2023).